SRSF5 (serine and arginine rich splicing factor 5)
Diseases named in the same sentence as SRSF5 in open-access papers (continued):
Sharing a sentence is not in itself a finding about the gene and the disease.
tumor (17 papers, 2017 to 2025). "The increased expression of SRSF5 was associated with higher tumor grade (P = 0.0327)." (PMID 29942010, 2018). "Downregulation of SRSF5 in oral squamous cell lines retarded cell growth, cell cycle progression, and tumor growth." (PMID 39000035, 2024). "The identification of the LINC01852/TRIM72/SRSF5/PKM2 signaling axis provides new insights into the molecular mechanisms underlying drug resistance and tumor progression, identifying new therapeutic targets for CRC." (PMID 38263157, 2024). "The results indicated that LINC01852 and SRSF5 potentially regulate multiple tumor-related signaling pathways." (PMID 38263157, 2024). "The downregulation of SRSF5 expression significantly inhibited cell growth and cell cycle progression, and tumor formation in vivo." (PMID 36505770, 2022). "We found that the level of phosphorylated SRSF5 elevated in tumor tissues with a high expression level of CLK1 by IHC." (PMID 33849617, 2021). "Here, the authors screened for SR proteins and identified SRSF5 stability is enhanced in response to glucose elevation to promote alternative splicing of CCAR1 which facilitates tumor growth." (PMID 29942010, 2018). "First, depletion of SRSF5 significantly reduced cell proliferation in cultured cells and tumor formation in xenografts." (PMID 29942010, 2018). "Here, through a screen of SRSF family, we identified SRSF5 as a glucose-inducible protein that promotes tumor cell growth via AS of CCAR1, a master of cell cycle arrest and apoptosis." (PMID 29942010, 2018). "Finally, we found that the expression of BQ in tumour samples from the SRSF5 knockdown group was significantly enhanced." (PMID 37190199, 2023). "The expression of BQ was significantly reduced in tumours with SRSF5 overexpression." (PMID 37190199, 2023). "Furthermore, xenograft experiments using these stable cell lines showed that the K125R and K125Q mutant markedly promoted tumor growth faster than the SRSF5-WT." (PMID 29942010, 2018). "We next investigated the mechanism by which SRSF5 controls tumor growth." (PMID 29942010, 2018). "Since high glucose is necessary for rapid growth of tumor cells, we asked whether SRSF5 is involved in the tumorigenesis." (PMID 29942010, 2018). "First, we found that overexpression of SRSF5 and PKM2 partially reversed the tumor suppressive effect of LINC01852." (PMID 38263157, 2024). "Mechanistically, LINC01852 functioned as a molecular scaffold to enhance the interaction of TRIM72 with SRSF5 and facilitate TRIM72-mediated degradation of SRSF5, thus inhibiting aerobic glycolysis, tumor growth and chemoresistance." (PMID 38263157, 2024). "Mechanistically, LINC01852 binds serine/arginine rich splicing factor 5 (SRSF5) and promotes its degradation and suppresses SRSF5-mediated alternative splicing of PKM2, thereby inhibiting aerobic glycolysis, tumor growth and chemoresistance." (PMID 38263157, 2024). "The methyl transferase METTL3 is up-regulated in brain tumors leading to the methylation of CPEB2 mRNA, which in turn stabilizes the splicing factor SRSF5 mRNA, leading to the incorporation of exon 7 in ETS-1 in models of the Blood–Tumor Barrier." (PMID 36064747, 2022). "Six overlapping AS events regulated by SF3B4 in tumor samples were finally verified, including 1 SE event (ATP2B4) and 5 RI events in 4 genes (SRSF5, PHF6, SNHG12, KIAA1217)." (PMID 33563334, 2021). "While some of these proteins such as SNRNP70 and SRSF5 are the components of the spliceosome complex, the others, namely, SORBS1, TPM2 and MYH11 were reported to have a role in tumor metastasis and development 41–43." (PMID 34728699, 2021). "SRSF5 promotes the alternative splicing of CCAR1 to produce CCAR1S proteins, which promote tumor growth by enhancing glucose consumption and acetyl-CoA production." (PMID 29942010, 2018). "In all three tumor classes the inclusion of these exons in SRSF4 and SRSF5 are lower than in NBS (−1 in Tumors), an indication of stabilization of these SRSF transcripts in the tumors." (PMID 28717182, 2017).
tumor (continued). "In contrast, overexpression of SRSFs (SRSF5 and SRSF8) might enhance the sensitivity of tumor to Src/ABL, mTOR1, and protein phosphatase inhibitors." (PMID 38015716, 2023). "We found that the knockdown of SRSF5 could make the cells TAM-resistant, as revealed by the tumour volume." (PMID 37190199, 2023). "SRSF5 is also overexpressed in OSCC and is essential for cell proliferation and tumor development." (PMID 36505770, 2022). "Xenograft assays showed that overexpression of CCAR1S, but not CCAR1L, rescued the effects of SRSF5-depletion and promoted the tumor development." (PMID 29942010, 2018). "SRSF5 (Serine and arginine-rich splicing factor 5), a member of the serine/arginine (SR)-rich family of pre-mRNA splicing factors, promotes the production of CCAR1S proteins by alternative splicing CCAR1 which enhances glucose consumption and acetyl-coA production, thus promoting tumor growth." (PMID 38020920, 2023).
infection (4 papers, 2012 to 2025). The state of being infected such as from the introduction of a foreign agent such as serum, vaccine, antigenic substance or organism. "Using a virtual structure‐based drug screening, anidulafungin is identified to target SRSF5 and shows potential for the inhibition of IAVs infections." (PMID 36257906, 2022). "Additionally, positive interactors of DCAF11 that were lost upon infection encompass splicing factors THRAP3 and SRSF5, the microtubule-associated protein MAP4, mitochondrial ribosomal protein MRPL12, and the TUFM mitochondrial translation elongation factor." (PMID 39383947, 2024). "Therefore, we focused on the SRSF5 protein and western blotting further showed rising SRSF5 protein levels in an infection time‐course dependent manner of 6, 12, and 24 hpi." (PMID 36257906, 2022). "Knockdown of specific SR proteins, including SRSF4, SRSF5, and SRSF6, significantly reduced viral growth, highlighting their critical role in the infection process." (PMID 40522993, 2025). "RNA fluorescence in situ hybridization (FISH) to detect endogenous SRSF5 and M mRNA showed increasing nuclear colocalization of SRSF5 with M mRNA of PR8 virus infected A549 cells over 12 h of infection." (PMID 36257906, 2022). "Interestingly, infection-induced phospho-SR proteins, particularly SRSF4, SRSF5 and SRSF6, were notably enriched in the Golgi apparatuses and large protein complex fractions at 4 hpi, with virus-induced phosphorylation diminished by 8 hpi (EV-A71)." (PMID 40522993, 2025). "Anidulafungin could suppress the infection and replication of Zika virus and HIV in vitro, suggesting that the functional relationship between SRSF5 and viral gene splicing may also be present in different viruses." (PMID 36257906, 2022). "Taken together, absence of SRSF5 reduces influenza virus replication in human cells and in mice, and, in the latter, reduces severity of infection." (PMID 36257906, 2022).
SRSF5 also shares sentences with these, for which no sentence is quoted: colorectal cancer (3 papers); virus infection (2); acute lymphoblastic leukemia (1); acute myeloid leukemia (1); breast tumors (1); cervical cancer (1); colon adenocarcinoma (1); embryonal carcinoma (1); HIV-1 infection (1); infectious disease (1); lung (1); renal carcinoma (1); seminoma (1).